CD4 (CD4 molecule)
Diseases named in the same sentence as CD4 in open-access papers (continued):
Sharing a sentence is not in itself a finding about the gene and the disease.
infection (continued). "OC43-SARS-CoV-2 sequential infection of our mice showed that OC43 pre-exposure was protective against SARS-CoV-2, and this protection was partly dependent on OC43-elicited CD4+ T cells." (PMID 38278784, 2024). "Despite the impaired B cell and humoral response, patients under rituximab showed an intact innate, CD8 T-cell and IFN-γ specific CD4+ and CD8+ T-cell response after infection and vaccination." (PMID 39257951, 2024). "RANKL is primarily expressed on activated CD4+ and CD8+ T cells and upregulated by T-cell receptor stimulation during infection." (PMID 38509997, 2024). "We show that CD4+ T cell help, including CD40L-CD40 signaling, is required during early acute infection for the generation of functional effector CD8+ T cell subsets." (PMID 39392861, 2024). "Immunizing C3H/HeN mice with recombinant YbgF resulted in the proliferation of IFNγ secreting CD4+ and CD8+ T cells and fewer bacteria in the spleen, liver, and lungs following infection with R. rickettsia." (PMID 38567021, 2024). "Early in infection, IFN-γ is derived from CD8 T cells and NK cells, and the initial IFN-γ synergizes with IL-12 to differentiate CD4 T cells into Th1 cells." (PMID 39759447, 2024). "While activated CD4+ T cells prevailed in reinfected mice, the memory phenotype of CD8+ T cells characterized animals exposed to a single infection." (PMID 38892340, 2024). "Vaccination of male and female mice revealed a similar interplay where memory CD4 T cells in females and antibodies in male ejaculate synergized to elicit sterilizing immunity against transmission, suggesting vaccination of both sexes could be ideal for reducing infection prevalence in humans." (PMID 39043447, 2024). "Our flow cytometry analysis revealed a higher population of both CD4+ and CD8+ T cells in WT and CNA25 primary-challenged mice at 3 h post infection, and subsequently, they reduced." (PMID 38783167, 2024). "Strong HCV-specific CD4+ and CD8+ T cell responses are observed among animals that clear the infection; in contrast, weaker T cell responses are observed among animals that progress to chronic HCV infection." (PMID 38668286, 2024). "After controlling for changes in surface marker expression frequency, the infection frequency of CCR5, α4β7, CCR5 + α4β7, CXCR4, and CD69 expressing CD4+ T cells remained greater in the EM of women following menopause." (PMID 39872519, 2024). "A recent study using a novel IFN© reporter mouse, demonstrated that CD4+ T, CD8+ T, ©δ T and NK cells all express IFN© during Tg infection." (PMID 38950025, 2024). "At 30 days post‐infection OM‐TB‐TKO and Y‐TB‐TKO mice had comparable frequencies of CD25+ CD4+ T cells, which were both significantly higher than that of O‐TB‐TKO mice." (PMID 39039808, 2024). "These immune cells activate innate immunity, with antigen-specific IFN-γ-secreting CD4+ and CD8+ T cells infiltrating infected tissues to control and eliminate infection." (PMID 38698906, 2024). "infection among PLWH include having diarrhea, being naïve to antiretroviral therapy, and having a CD4+ T cell count below 200 cells/mm3." (PMID 39597540, 2024). "Within the CD4+ T cell compartment of CHHIL participants, ten clusters changed significantly in frequencies throughout the infection." (PMID 39013877, 2024). "Surface CD4 and CXCR4 expression was demonstrated to be equivalent at the time of infection in control or SLFN14 cells by flow cytometry, and cell supernatant HIV-1 p24 levels were normalized to the % of CD4/mCherry CXCR4 double positive cells." (PMID 38675845, 2024). "EMT CD4+ T cells express substantially higher levels of CCR5 than newly activated CD4+ T cells, making them more permissive to infection by CCR5-tropic HIV-1." (PMID 38580979, 2024). "Following infection, the respiratory tract recruits SARS-CoV-2–specific CD4+ and CD8+ T cells, a substantial proportion of which release the cytotoxic substance granzyme B (GzB)." (PMID 39178263, 2024).
infection (continued). "While recruitment of neutrophils to the lung occurs by 3 days post-infection with IAV, CD4 T cells, CD8 T cells, and B cells accumulate in the lung from around day 9 dpi in both WT and MMTV-Her2 mice." (PMID 38645169, 2024). "Preclinical studies have shown that nasally delivered vaccines are more effective than parenterally delivered vaccine at inducing respiratory CD4 TRM and preventing infection of the nasal mucosa." (PMID 38290045, 2024). "Once the antigen is processed and presented on MHC complexes (MHCs) I and II, this can alert CD4+ and CD8+ T cells in response to an infection." (PMID 39066358, 2024). "Reports show that CD4+ Trm cells are located in the dermis or LP, while CD8+ Trm cells express CXCR9 and CXCR10 and are located in the epidermis or epithelium during infection in the skin and mucosa." (PMID 39352752, 2024). "The recruitment of CD4+ and CD8+ T cells by the influx of neutrophils was a beneficial immune phenomenon that helped to clear the infection." (PMID 39093884, 2024). "Next, we combined models of HIV-1 transmission, heritability and disease progression to understand whether available data suggest a faster CD4+ T cell decline would be expected to associated with multiple variant infection, without an explicit dependency between the two." (PMID 39471873, 2024). "Conversely, a CTL phenotype was characterized by high levels of both CD4+ and CD8+ (CD4+CD8+high), which demonstrated the ability to destroy infected cells within 3–6 h post infection." (PMID 38932335, 2024). "We showed that pp65 and gB proteins were recognized by CD4+ T cells, and IE-1 and pp65 proteins were recognized by CD8+ T cells; the pattern of T cell reactivity was the same in the early and late phases of infection." (PMID 39336935, 2024). "Taken together, these data suggest that in response to infection, PEP-619WW mice have more effector-like CD4 T cells (cluster 1 and 4) as compared to PEP-WT mice." (PMID 38512979, 2024). "More work will be required to understand the role of CD4-derived IFN-γ in limiting replication within the intestine and these other disseminated sites of infection." (PMID 38166152, 2024). "While less frequently studied than CD4+ Treg, FoxP3+ as well CD8+ Treg can also be induced by various infections." (PMID 39140728, 2024). "Using this approach, we report that caspase-1 is required for optimal parasite control, promoting CD4+ T cell IFN-γ production and enhancing neutrophil and monocyte recruitment to the initial site of infection." (PMID 39446964, 2024). "The infection of MOLT-4/CCR5 cells with AAV-Eliminator viruses results in the protein expression of Exo-Tat, IL16lamp2b and CD4-αCD3 in MOLT-4/CCR5 cells." (PMID 39203549, 2024). "Nasal discharge was a particularly prominent feature of late infection in WC1+ γδ T cell-depleted sheep, whilst clinical scores of the feet (heat and redness) were the highest in the CD4+ T cell-depleted sheep." (PMID 38357545, 2024). "Correspondingly, CD4+ and CD8+ T lymphocytes protein expression increases following primary infection than secondary infection." (PMID 38492183, 2024). "The frequency of activated CD4 T cells decreased throughout infection, while that of the GZMA CD4 cluster increased at 3 and 7 DPI." (PMID 38887303, 2024). "In contrast, the second peak of IOP was caused by the infiltration of adaptive immune cells, such as CD8, CD4, and NKT cells, eight days after infection." (PMID 39134803, 2024). "We then infected these chimeras with LCMV-Cl13 and stained activated T cells with tetramers for the immunodominant CD4+ and CD8+ epitopes (GP66:I-Ab and GP33:Db, respectively) 45 days post-infection." (PMID 38300945, 2024). "We identified changes in innate cells, primarily the innate lymphoid cells (ILC, NK cells) and adaptive immune cells (CD4+ and CD8+ T cells) over this time course of infection." (PMID 38543837, 2024).
infection (continued). "The spleen contains various immune cell populations, including CD4+ and CD8+ T cells, which are crucial for immune response of anti‐infection." (PMID 38770891, 2024). "They followed the GFP+ CD4 T-cells up to 60 days post-infection and found that the number of GFP+ CD4 T-cells was continuously increasing." (PMID 38788198, 2024). "The replication capacity of these viruses was measured post-infection of PBMCs or CD4 cells, polyclonally expanded from PBMCs by bispecific anti-CD3/CD8 mAb, from a single healthy donor at a multiplicity of infection of 0.05." (PMID 39599821, 2024). "Elevated CD4+ T-cell activation, coupled with a high HIV load, accelerates cell death and further infection." (PMID 39066368, 2024). "However, as the exact time of SARS-CoV-2 infection in the children group could not be defined, we cannot fully exclude that the higher magnitude of SARS-CoV-2-specific CD4+ T cells observed in the adult group could be related to a more recent infection compared to the children group." (PMID 38235336, 2024). "We further investigated the influence of semen on the infection of HIV-1 T/F virus and its neutralization by bNAbs in primary CD4+ T cells, key target cells for HIV." (PMID 38501840, 2024). "After 6 days of viral exposure, flow cytometry was used to determine CD4+ T cell and CD14+ cell infection frequency in the mixed cell cultures." (PMID 39872519, 2024). "The frequencies (in %) of CD4+ T cells, CD8+ T cells, and CD4+/CD25+FoxP3+ regulatory T cells (Tregs) in the lung and thymus were determined on day 3, 6 and 9 post infection." (PMID 38979428, 2024). "Evidence indicates that in patients with IM, the number of CD4+ T lymphocytes specific to EBV constitutes up to 1% of the total circulating cells, decreasing to approximately 0.1% after the resolution of the infection." (PMID 39066175, 2024). "The induction of CD4+ TRM cells has shown promise in experimental immunization, leading to protection against Leishmania challenge infections." (PMID 38469319, 2024). "After an acute phase of the infection, HIV-1 becomes latent in a fraction of usually long-lived CD4+ T cells, establishing a reservoir that has the proviral DNA HIV-1 genome integrated into the host cell genome." (PMID 38675843, 2024). "The level of response produced by CD4+ was lower than that produced by CD4+ + CD8+ T-cells in all vaccination regimen, except response induced by 2 doses of PZ and prior infection." (PMID 38572317, 2024). "A compartment of these cells transforms into CD4+ TRM cells, which in the secondary challenge infection produce IFN-γ to activate macrophages." (PMID 38469319, 2024). "The frequency of CD107a+ T-cells also significantly increased at early infection; p = 0.0273 in CD8+ and p = 0.0068 in CD4+ T-cells." (PMID 38543812, 2024). "One cause of immunosuppression which has been shown in case studies to lead to SARS-CoV-2 long-term infection and evolution is uncontrolled HIV infection resulting in extensive CD4 T-cell depletion, termed advanced HIV disease." (PMID 38491050, 2024). "We found that patients with shorter hospitalization have more robust of both IFNγ+CD4+ and CD8+ T cell responses than those with extended hospitalization (P < 0.05) during the early phase post-infection (7–14 dps)." (PMID 38811527, 2024). "Infection-induced SARS-CoV-2-specific memory CD4+ T-cells are predominantly T-helper 1 (Th1) cells, T-follicular helper (Tfh) cells, and CD4-cytotoxic (CTL) cells." (PMID 39340081, 2024). "Similar to memory CD8+ T cells, CD4+ TIA cells can be stimulated in vitro to produce IFN-γ by the cytokine combination IL-12 + IL-18, both of which are present during Lpn infection." (PMID 38838013, 2024). "At 12 weeks post Mtb M2 infection, lung cells were ex vivo stimulated with ESAT-6 and PPD, and Ag-specific CD4+ T-cells were then analyzed using multi-color flow cytometry." (PMID 38459038, 2024).
infection (continued). "Ultimately, by weakening the host’s immune system by CD4+ T-cell depletion, HIV deprives the human body of a potent weapon to fight infection." (PMID 39339243, 2024). "Given that iCoV2 + Alum induced type 2 inflammation during heterologous infection, suggesting a strong TH2-biased immune response, we next tested the role of TH cells via CD4+ cell depletion in iCoV2 + Alum-vaccinated animals prior to SHC014 challenge." (PMID 38702297, 2024). "For BA.2 antigens, significantly associated factors with the immune responses were the time elapsed since the last vaccine dose or infection, anti-N IgM (CD8+ T cells) and anti-S IgG (CD4+ T cells)." (PMID 38651389, 2024). "Distinguishing between the CD4 and CD8 immune compartments and the dynamics of activation after vaccination and infection can provide greater nuance for understanding how protective cellular responses are mediated." (PMID 39260039, 2024). "During infection, there is a reduced expression of MHC-II, which is essential for the maturation of CD4+ T lymphocytes." (PMID 39728964, 2024). "In CD4+ T cells, the frequency of naïve (TN) cells increased, but the frequency of central memory (TCM) cells decreased in PLWH post-breakthrough infection compared to pre-breakthrough infection." (PMID 38140668, 2023). "For Zika virus (ZIKV) it was shown that functional CD4+ and CD8+ T cell responses were required to control and clear infection in ZIKV NS1-vaccinated mice, despite the presence of high anti-NS1 antibody levels." (PMID 37483628, 2023). "In contrast, pH1N1 infection induced the greatest AAV NP response and strong CD8 TNF production in TBLN and CD4 TNF in TBLN and PBMC." (PMID 37153548, 2023). "At day 5 after infection, low numbers of CD4+ and CD8+ T cells were detected in BAL and these increased markedly, particularly for CD8+ T cells, by day 10 after infection." (PMID 36744765, 2023). "Autophagy has been shown to facilitate antigen processing to major histocompatibility complexes (MHCs) I and II to alert CD4+ and CD8+ T cells to an infection." (PMID 37242496, 2023). "Infection-induced responsiveness prior to vaccination was mainly detected in CD8+ T cells, while vaccine-induced T-cell responses were mostly by CD4+ T cells." (PMID 38193077, 2023). "At one week post infection, we observed a significant increase in the percentage of activated (CD44+) CD4+ T cells in μMT mice." (PMID 37721965, 2023). "Several studies have shown how CD4+, CD8+, and regulatory T cells are significantly impaired in severe cases of infection." (PMID 37457959, 2023). "The frequency (%) and absolute cell count (#) of PD-1+ cells among CD4+ and CD8+ T cells showed a gradual fold-increase over infection time." (PMID 37691941, 2023). "The highest frequency of each population was observed at 1 month post-infection, (Median: 0.0093%; 0.012%; and 0.018% for IL2 + / IFNγ-; IFNγ + /IL2-; and IL2 + /IFNγ + CD4 + T cells, respectively)." (PMID 37974069, 2023). "Frequencies of both CD4+ and CD8+ T cells returned to near pre-infection baseline levels by week 12 after IV BCG." (PMID 37090620, 2023). "Changes in the gene expression of CD4 and CD8 markers can provide important information about the state of the immune system and its response to infection or disease." (PMID 37465154, 2023). "After adoptive transfer of CD4+ T cells, IFN-γ secretion by CD8+ T cells of CD4+T+rEg.P29+CpG+Infection group with rEg.P29 stimulation was significantly increased when compared with that without stimulation." (PMID 38151996, 2023). "Meanwhile, the mature T-cell markers of the T-cell lineage, including CD4, CD8, and CD3, were downregulated in the spleen after infection." (PMID 36835242, 2023). "Upon acquiring the infection, HIV specifically attacks CD4+T lymphocytes in humans, resulting in the decrease or dysfunction of CD4+T lymphocytes." (PMID 38148912, 2023).
infection (continued). "Overall, in the pre-infection phase of IAV infection, the differentiation of CD4+ helper T lymphocytes shows a predominant proliferation of Th1 and Th17, which have a role in promoting immune clearance of pathogens." (PMID 37928517, 2023). "Previous studies have shown the presence of an inflammatory infiltrate based on cells as CD3+, CD4+, CD8+, and γδTCR+, and NKp46+ in caruncles from animals infected at different stages of infection." (PMID 37520552, 2023). "We found that the frequencies of HLA-DR+CD38+CD4+ and HLA-DR+CD38+CD8+ T cells were higher in PLWH post-breakthrough infection than in those who were pre-infected." (PMID 38140668, 2023). "These markers enable the identification of the larger pool of LCMV-specific CD4+ and CD8+ T cells that are responding to the infection." (PMID 36792599, 2023). "CD4+ and CD8+ T cells trafficked to the MEs following infection and were necessary to robustly protect against secondary challenge." (PMID 38125908, 2023). "LAVs mimic natural infection, which is known to induce SARS-CoV-2-specific CD4+ Th1 cells secreting IFN-γ49." (PMID 37012419, 2023). "We thus infected primary CD4+ T cells with CH058 TF; treated the cells with IFN-β (or PBS) 24 h later; and then examined BST-2, NTB-A, and CD48 expression 48 h post infection by flow cytometry." (PMID 37404017, 2023). "We also monitored the levels of activated CD4 and CD8 T cells throughout the course of the infection." (PMID 37112931, 2023). "Following infection with BCG, intracellular IFN-γ induction was mildly impaired in CD4+ T cells and more severely in MAIT and Vδ2+ γδ T cells of IL-23R-deficient patients, and this impairment was not rescued by exogenous IL-12." (PMID 36763636, 2023). "The T cell responses show durable and polyfunctional virus specific memory CD4 and CD8+ T cells in infected patients up to 8 months after infection, and specificity was observed to a range of SARS‐CoV‐2 antigen." (PMID 37692793, 2023). "Since the IgG1 alone cannot protect the dams and pups from N. caninum progression, the CD4+ and CD8+ T cells must be essential in preventing N. caninum intracellular multiplication at the early and chronic stages of infection." (PMID 38110570, 2023). "Flow cytometric analysis showed that at 24 weeks post-infection, the frequency of IFN-γ-producing CD4+ T cells in the lungs of tuberculous μMT mice is lower than that detected in WT animals (p<0.03)." (PMID 36888692, 2023). "While the numbers of Ifnγ+ CD4 T cells remained stable, IAV infection did lead to a sustained increased in Ifnγ+ CD8 T cells up to 40 days post-infection." (PMID 37842651, 2023). "Our CSP types were defined by polymorphic residues in the known CD4+ and CD8+ T-cell epitopes in the C-terminal domain, suggesting that T-cell responses are primed more effectively by symptomatic infections." (PMID 37307293, 2023). "Similar to what has been observed in convalescent, as well as vaccinated infection-naïve healthy individuals, we observed a TCM-dominated CD4+ spike-specific T cell population and a tendency of increased TSCM/CM T cell frequencies in the CD8+ compartment." (PMID 37437015, 2023). "For the progressor animals 165 and 186, CD4 and CD8 T cells progressively and profoundly decreased throughout the asymptomatic phase of infection." (PMID 37632117, 2023). "When investigating the CD4+ and CD8+ subtypes, we observed a drastic increase in CD4+ and CD8+ T effector cells (Te) throughout infection." (PMID 37112973, 2023). "The routine follow-up of these infections considering the HIV viral load and CD4/CD8 counts is important for the quality of life of HIV patients." (PMID 37887742, 2023). "They found that patients with SARS-CoV-2 pneumonia had more CD4+ and CD8+ T cells in their alveolar area than patients with other infections." (PMID 37240926, 2023).